MTAP (methylthioadenosine phosphorylase)
Description:
Catalyzes the phosphorolytic cleavage of S-methyl-5'-thioadenosine (MTA) to adenine and 5-methylthioribose1-phosphate. Involved in the breakdown of MTA, a major by-product of polyamine biosynthesis. Responsible for the first step in the methionine salvage pathway after MTA has been generated from S-adenosylmethionine. Has broad substrate specificity with 6-aminopurine nucleosides as preferred substrates.
Synonyms: MSAP; c86fus; BDMF; DMSFH; DMSMFH; HEL-249; LGMBF
Tractability: Small molecule: a structure with a bound ligand is known; a high-quality ligand is known; it has a high-quality binding pocket; it belongs to a druggable protein family. PROTAC: ubiquitination databases record sites on it; its protein half-life has been measured; a small molecule that binds it is known.
Target class: Enzyme
Gene: Protein-coding gene on chromosome 9 (21,802,636 to 21,937,651, forward strand). Ensembl gene ENSG00000099810.
Subcellular location: Cytoplasm; Nucleus
Subcellular location (Human Protein Atlas): Cytosol; Nucleoplasm
Pathways (Reactome):
Immune System: Gene and protein expression by JAK-STAT signaling after Interleukin-12 stimulation
Metabolism: Methionine salvage pathway
Gene Ontology:
Molecular function: protein binding; S-methyl-5-thioadenosine phosphorylase activity; 1,4-alpha-oligoglucan phosphorylase activity; catalytic activity; pentosyltransferase activity
Biological process: nicotinamide riboside catabolic process; nucleobase-containing compound metabolic process; nucleoside metabolic process
Cellular component: cytosol; extracellular exosome; cytoplasm; nucleus
Genetic constraint (gnomAD): Loss-of-function variants: 30 observed, 27.31 expected, observed/expected ratio (o/e) 1.1, 90% interval 0.82 to 1.49. The upper end of that interval is the gene's LOEUF score, 1.49, which puts it in group 6 of 6, group 1 being the genes least tolerant of losing a copy. Missense variants: 331 observed, 331.35 expected, observed/expected ratio (o/e) 1, 90% interval 0.91 to 1.09. Synonymous variants: 131 observed, 116.85 expected, observed/expected ratio (o/e) 1.12, 90% interval 0.97 to 1.3.
Gene-disease validity (ClinGen):
ClinGen rates the evidence that MTAP causes each of these diseases.
diaphyseal medullary stenosis-bone malignancy syndrome (autosomal dominant): Moderate. Diaphyseal medullary stenosis with malignant fibrous histiocytoma is a very rare autosomal dominant bone dysplasia/cancer syndrome characterized clinically by bone infarctions, cortical growth abnormalities, pathological fractures, and development of bone sarcoma (malignant fibrous histiocytoma).
Homologues: Orthologues: macaque MTAP (100% identical), rabbit MTAP (98% identical), chimpanzee MTAP (97% identical), guinea pig Mtap (95% identical), dog MTAP (94% identical), mouse Mtap (94% identical), pig MTAP (93% identical), guinea pig MTAP (85% identical), zebrafish mtap (79% identical), tropical clawed frog mtap (76% identical), rat Mtap (74% identical), Drosophila melanogaster Mtap (60% identical), and 2 more. Paralogues in human: PNP (25% identical).
Diseases named in the same sentence as MTAP in open-access papers:
MTAP is named in the same sentence as 167 diseases in open-access papers, as found by Europe PMC text mining. Sharing a sentence is not in itself a finding about the gene and the disease. The quoted sentences say what the papers report.
melanoma (59 papers, 2010 to 2026). A malignant, usually aggressive tumor composed of atypical, neoplastic melanocytes. "In various malignancies, including mesothelioma, glioma, and melanoma, loss of MTAP expression correlates with advanced disease and increasingly aggressive clinical behavior." (PMID 41596618, 2026). "Although the body of literature remains limited, retrospective studies have consistently shown that combined loss of p16 and MTAP expression is strongly associated with lesions ultimately classified as melanoma or high-risk melanocytomas." (PMID 41596618, 2026). "Within primary melanomas, loss of MTAP expression correlated with increased cellular proliferation, as indicated by a Ki67-labeling index ≥ 5% (p = 0.04)." (PMID 41596618, 2026). "The combined loss of CDKN2A and MTAP is a recurrent event in several malignancies, including mesothelioma, glioma, and melanoma, suggesting a broader biological linkage within the 9p21 locus." (PMID 41596618, 2026). "In line with this notion, recent studies have described a worse response of 9p21/MTAP‐deficient melanoma, non‐small cell lung cancer, and metastatic urothelial cancer to CPIs as compared to 9p21/MTAP‐proficient cancers." (PMID 39668577, 2025). "For example, of the 16 total genes driving the association between melanoma and nevus count, only two (MTAP and ERVFRD‐3) were shared by all three tissues, and six (MAFF, HEBP1, HTR7P1, EMP1, GPRC5A, C9orf66) were specific to melanocyte." (PMID 38308491, 2024). "Multiple SNPs in this locus were also associated with cis regulatory activity of MTAP, a well‐known melanoma susceptibility gene." (PMID 38308491, 2024). "MTA concentrations within MTAP-deficient human melanoma cell lines have been reported to be up to 140 nM and up to 1,000 nM within the supernatant." (PMID 33123121, 2020). "The association of HERC2/OCA2 and CKDN2A/MTAP loci with melanoma risk were confirmed in subsequent meta-analyses." (PMID 28973033, 2017). "We also uncovered a significant association in the CDKN2A/MTAP region, previously reported in two separate GWAS of melanoma in Caucasians." (PMID 28973033, 2017). "Recent studies reported a significant association of the MTAP SNPs rs7023329 (intron 2) and rs10811629 (intron 5) with melanoma incidence and number of melanocytic nevi." (PMID 27479139, 2016). "Further, the MTAP polymorphism rs10757257*G in intron 1 was found to be significantly associated with melanoma risk in adults and, in particular, with superficial spreading and nodular melanoma subtypes." (PMID 27479139, 2016). "This supports our previous finding, that loss or reduction of MTAP expression in melanoma is more often the result of hypermethylation of the promoter region than chromosomal deletion of the MTAP locus." (PMID 27479139, 2016). "As a matter of fact, the odds ratio of 1.746 observed for MTAP rs7023954*G is quite similar to that reported for MTAP rs10757257*G and melanoma risk in adults (OR = 1.32, 95% CI = 1.14–1.54)." (PMID 27479139, 2016). "Spurred by reports of an association of the MTAP locus with melanoma risk, this study aimed at investigating the frequency of rs7023954 genotypes in normal skin as well as primary and metastatic melanoma tissues and cell lines." (PMID 27479139, 2016). "The rs751173 polymorphism located in an intergenic region between the interferon, epsilon (IFNE) and the MTAP genes showed association with a statistical significant increased melanoma risk." (PMID 23816148, 2013). "A statistically significant decreased risk of melanoma was also observed for the carriers of the G-variant of the polymorphism rs10811629 located in intron 5 of MTAP gene (OR 0.80, 95% CI 0.66-0.98)." (PMID 23816148, 2013). "The polymorphism rs7023329 located in intron 2 of MTAP that tagged 10 additional variants showed a statistical significant association with decreased risk of melanoma." (PMID 23816148, 2013).
melanoma (continued). "For population based melanoma, recent large scale genome wide association studies in melanoma and naevi have discovered new common low penetrance genes (MTAP, PLA2G6, TERT and IRF4 for example) associated with both naevi number and melanoma." (PMID 23796690, 2013). "We have recently shown that there is a clear association between MTAP expression in the primary melanoma and melanoma progression and, even more importantly, response to interferon treatment." (PMID 22685558, 2012). "Immunohistochemical analysis comparing benign melanocytic nevi to melanomas has shown an inverse association between MTAP protein expression and progression of melanocytic tumors." (PMID 22220281, 2011). "Concordant loss of both markers strongly supports melanoma or high-risk melanocytoma, while MTAP retention may predict responsiveness to adjuvant interferon therapy." (PMID 41596618, 2026). "Additionally, the potential clinical relevance of MTAP expression in melanoma was further evaluated in studies assessing its association with clinicopathologic features and therapeutic response." (PMID 41596618, 2026). "Importantly, we were also able to extend our analysis of germline alleles in melanoma patients to identify candidate functional variants at loci including MTAP/CDKN2A, where risk alleles were associated with phenotypes such as naevus count, and CASP8." (PMID 35357426, 2022). "Therefore, in melanoma cells, the loss of MTAP expression leads to a significant decrease in protein methylation through accumulation of MTA." (PMID 35311114, 2022). "In addition, MTAP deficiency is a predictive marker for the response to adjuvant interferon therapy in melanoma patients." (PMID 33123121, 2020). "Interestingly, loss of MTAP activity or deletion of the MTAP gene has been reported to occur in a variety of primary tumors, such as acute lymphoblastic leukemia, non-small-cell lung cancer, and melanoma." (PMID 29212228, 2017). "In case of malignant melanoma, the loss of MTAP expression is linked to a higher invasive potential, leading to the hypothesis that loss of MTAP expression might contribute to metastasis of malignant melanoma." (PMID 28337200, 2017). "Genetic association studies have also suggested that genetic polymorphism in MTAP may modulate the risk of melanoma." (PMID 27479139, 2016). "In addition, re-expression of MTAP in either a MTAP-deleted melanoma cell line or a gastric carcinoma cell line causes reduced cellular invasion in vitro." (PMID 25387827, 2014). "Loss of MTAP expression in melanoma is mainly due to hypermethylation of the promoter region." (PMID 23816148, 2013). "It was suggested that loss of MTAP expression in malignant melanomas might have an impact on therapeutic success by compromising tumor response to interferon treatment through its impact on STAT1 activity." (PMID 23816148, 2013). "Loss of MTAP activity has been hypothesized to play a role in malignant melanoma." (PMID 33096795, 2020). "Cytoplasmic MTAP expression was detected in 227 of the 315 informative cases (72.1%) and significantly reduced in primary malignant melanomas and melanoma metastases compared with benign nevi (p < 0.001 for both)." (PMID 41596618, 2026). "Using a nearby rare exonic variant in MTAP (rs755147810) on the deletion haplotype, we searched for deletion carriers in WES data from high-risk melanoma patients and controls and identified 22 cases and a single control carrying rs755147810 and the deletion." (PMID 42183343, 2026). "Among the 26 patients with MTAP-positive melanomas and tumor recurrence, those who received adjuvant interferon therapy (n = 18) exhibited a significant survival benefit compared to those who did not receive interferon (n = 8) (p = 0.009)." (PMID 41596618, 2026).
melanoma (continued). "Early observations indicated numerous objective responses in patients with melanoma, gallbladder adenocarcinoma, mesothelioma, non-small-cell lung cancer, and malignant peripheral nerve sheath tumors in the presence of MTAP deletion." (PMID 41465382, 2025). "Among the genes we identified, many are known melanoma susceptibility genes including CASP8, ARNT, and OCA2 (downregulated), PARP1, SETDB1, MTAP, SLC45A2, and MC1R (upregulated), and MX2 (both up‐ and downregulated)." (PMID 38308491, 2024). "When MTAP is downregulated in melanoma, 5′-methylthioadenosine (MTA) builds up and promotes tumor spread by preventing protein methylation and activating the extracellular signal-regulated kinase (ERK) signal." (PMID 36913304, 2023). "Collectively, these findings implied that the MTAP-ANRIL fusion gene promoted melanoma cell migration, invasion and proliferation." (PMID 37277447, 2023). "Inhibition of the JNK and p38 pathways in MTAP-ANRIL melanoma cells increased the expression level of E-cadherin but decreased the expression levels of SNAIL1, N-cadherin, cyclin B1 and cyclin D1 that were increased by MTAP-ANRIL." (PMID 37277447, 2023). "It has shown a selective in vitro anti-neoplastic activity against methylthioadenosine phosphorylase (MTAP)-deficient tumours such as leukaemias, brain tumours, non-small-cell lung cancers, breast cancers, melanomas, pancreatic cancers, and sarcomas." (PMID 37090313, 2023). "We found that MTAP-ANRIL overexpression in melanoma cells inhibited the expression of MTAP and decreased the expression of E-cadherin but increased the expression of N-cadherin, important markers of EMT." (PMID 37277447, 2023). "The recurrent MTAP-ANRIL fusion gene was reported to have a frequency of greater than 7% in melanoma in our previous study." (PMID 37277447, 2023). "Consistently, MTAP homozygous deletion occurs frequently in cancers such as glioblastomas, melanomas, and pancreatic cancer." (PMID 37179124, 2023). "Collectively, these findings indicated that MTAP-ANRIL can promote melanoma cell migration and proliferation by activating the JNK and P38 signaling pathways." (PMID 37277447, 2023). "Our results showed that MTAP-ANRIL fusion gene regulated melanoma migration and invasion abilities via EMT-like process, but the EMT transcriptional factors which involved in the experimental model is unclear." (PMID 37277447, 2023). "In the current study, we found that MTAP-ANRIL promoted melanoma cell metastasis by inducing EMT-like process through downregulating E-cadherin and upregulating N-cadherin." (PMID 37277447, 2023). "Quite possibly, MTAP-ANRIL gene fusions play a role in melanoma metastasis by acting on wild-type MTAP." (PMID 37277447, 2023). "We used a transwell assay to evaluate the migration and invasion abilities of melanoma cells overexpressing MTAP-ANRIL compared with control cells." (PMID 37277447, 2023). "MTAP has been reported as a tumor suppressor gene in various types of human cancers, such as leukemia 11, lymphoma 34 and melanoma 16, 35, which is likely to be a potential target for cancer treatment." (PMID 35541910, 2022). "PRMT6 was found to be expressed at reduced levels in melanoma compared to melanocytes, early studies have shown that the expression of methylthioadenosine phosphorylase (MTAP), which is involved in tumorigenesis, is significantly reduced in melanoma." (PMID 35311114, 2022). "9p21 status was inferred based on transcriptional expression levels of both CDKN2A and MTAP, the same in the melanoma cohorts." (PMID 34556668, 2021). "We cloned both alleles and expressed them using both a rabbit reticulocyte lysate translation system as well as transient and stable transfection of an MTAP-null melanoma cell line." (PMID 27479139, 2016). "Screening of cDNA from 64 melanoma cell lines resulted in detection of fusion transcripts in 13 (20%) cell lines that involved exons 4-7 of the MTAP and exon 2 or 5 of the ANRIL genes." (PMID 26909863, 2016).
melanoma (continued). "MTAP is reported to show low expression in malignant melanoma cells and conversely its substrate i.e., 5′-deoxy-5’-(methylthio) adenosine (MTA) has higher expression in melanoma cells compared to normal melanocytes." (PMID 23816148, 2013). "MTAP is located closely to the CDKN2A locus and melanoma tumours often show loss of both loci and it is therefore possible that there are interactions between these two genes." (PMID 23796690, 2013). "A tissue microarray study in malignant melanoma demonstrated a significant reduction of MTAP in melanomas and metastases compared with nevi." (PMID 21647268, 2011). "Among the genes found to be downregulated in the UVM subtracted library, several were previously associated with melanoma, such as melanocytic markers TYRP1, EDNRB, MTAP, and sex determining region Y box 4 (SOX4)." (PMID 21647268, 2011). "It has been suggested that loss of expression of the gene has prognostic implications for melanoma and codeletion of MTAP with CDKN2A has been investigated in a number of cancers." (PMID 20140953, 2010). "The second study demonstrated that methylthioadenosine phosphorylase (MTAP), a gene adjacent to CDKN2A, and another locus encompassing PLA2G6 (a member of the phospholipase A2 gene family) both showed an association with melanoma risk." (PMID 21203498, 2010). "When correlated with molecular data, MTAP loss showed 100% specificity and a positive predictive value of 100% for detecting CDKN2A homozygous deletion, but only 41% sensitivity, confirming that MTAP immunostaining alone lacks optimal sensitivity for detecting all CDKN2A-inactivated melanomas." (PMID 41596618, 2026). "In their series, MTAP loss was observed in 10% of melanomas and in none of the nevi, while p16 loss occurred in 59% of melanomas." (PMID 41596618, 2026). "Taken together, these findings indicate that MTAP loss is associated with malignant progression and increased proliferative activity in melanoma, while retained MTAP expression may predict responsiveness to interferon therapy." (PMID 41596618, 2026). "This suboptimal sensitivity reflects the molecular architecture of the 9p21 locus, where smaller deletions may selectively involve CDKN2A while sparing the adjacent MTAP gene, resulting in melanomas that are p16-negative but retain MTAP expression." (PMID 41596618, 2026). "However, some studies report as high as 55% incidence of MTAP deletion in patients with malignant peripheral nerve sheath tumor, 40% in patients with glioblastoma and pancreatic cancer and 25% in melanoma." (PMID 41465382, 2025). "Indeed, all genes associated with nevus count or cutaneous nevi in cluster 6 (MTAP, TUBBP1, PLA2G6, ERVFRD.3, TMEM184B, BAIAP2L2) were only associated with melanoma." (PMID 38308491, 2024). "In parallel, we found that MTAP-ANRIL promoted melanoma cell metastasis and proliferation in vivo." (PMID 37277447, 2023). "Another explanation for the loss of MTAP expression in those cases with heterozygous MTAP deletion could be MTAP silencing, as has been described in melanoma, where epigenetic dysregulation of MTAP and other genes contribute to tumor progression and invasion." (PMID 37894345, 2023). "Furthermore, we found that MTAP-ANRIL-enhanced melanoma cell migration and proliferation were abolished by pretreatment with JNK and p38 inhibitors." (PMID 37277447, 2023). "In addition, we demonstrated that MTAP-ANRIL enhanced melanoma cell proliferation by upregulating the expression of the cell cycle regulators, cyclin B1 and cyclin D1." (PMID 37277447, 2023). "Overexpression of MTAP-ANRIL significantly increased melanoma cell proliferation." (PMID 37277447, 2023). "There have been two subsequent solid tumor studies of 9p21.3 loss (inferred from two genes on this band, CDKN2A and MTAP) reporting that 9p21.3 loss was associated with TME or ICT outcomes in lung adenocarcinoma, bladder cancer, melanoma, and small mixed solid tumor ICT cohorts." (PMID 36395141, 2022).